QRICH1 (glutamine rich 1)
Description:
Transcriptional regulator that acts as a mediator of the integrated stress response (ISR) through transcriptional control of protein homeostasis under conditions of ER stress. Controls the outcome of the unfolded protein response (UPR) which is an ER-stress response pathway. ER stress induces QRICH1 translation by a ribosome translation re-initiation mechanism in response to EIF2S1/eIF-2-alpha phosphorylation, and stress-induced QRICH1 regulates a transcriptional program associated with protein translation, protein secretion-mediated proteotoxicity and cell death during the terminal UPR. May cooperate with ATF4 transcription factor signaling to regulate ER homeostasis which is critical for cell viability. Up-regulates CASP3/caspase-3 activity in epithelial cells under ER stress. Central regulator of proteotoxicity associated with ER stress-mediated inflammatory diseases in the intestines and liver. Core component of the zincore complex, a heterotetramer that acts as a molecular 'grip' to stabilize transcription factors at DNA-binding sites across the genome, thereby controlling gene expression. The zincore complex binds specifically to zinc finger transcription factors, such as ZFP91, ZNF652, ZNF526 and PRDM15, and stabilizes them onto their cognate DNA motif. Involved in chondrocyte hypertrophy, a process required for normal longitudinal bone growth.
Synonyms: FLJ20259; VERBRAS; AB-DIP; VERBRAS1
Tractability: Antibody: UniProt places it where antibodies can reach, with high confidence; its Gene Ontology location is reachable by antibodies, with medium confidence. PROTAC: UniProt records ubiquitination sites on it; ubiquitination databases record sites on it; its protein half-life has been measured.
Gene: Protein-coding gene on chromosome 3 (49,029,707 to 49,094,545, reverse strand). Ensembl gene ENSG00000198218.
Subcellular location: Nucleus; Chromosome; Cytoplasm; Cell membrane
Subcellular location (Human Protein Atlas): Nucleoplasm
Gene Ontology:
Molecular function: DNA binding; protein binding
Biological process: endoplasmic reticulum unfolded protein response; integrated stress response signaling; intrinsic apoptotic signaling pathway in response to endoplasmic reticulum stress; PERK-mediated unfolded protein response; positive regulation of apoptotic process; positive regulation of DNA-templated transcription; response to endoplasmic reticulum stress
Cellular component: chromosome; cytoplasm; nucleoplasm; nucleus; plasma membrane
Genetic constraint (gnomAD): Loss-of-function variants: 14 observed, 83.83 expected, observed/expected ratio (o/e) 0.17, 90% interval 0.11 to 0.26. The upper end of that interval is the gene's LOEUF score, 0.26, which puts it in group 1 of 6, group 1 being the genes least tolerant of losing a copy. Missense variants: 638 observed, 959.55 expected, observed/expected ratio (o/e) 0.66, 90% interval 0.62 to 0.71. Synonymous variants: 363 observed, 377.13 expected, observed/expected ratio (o/e) 0.96, 90% interval 0.88 to 1.05.
Gene-disease validity (ClinGen):
ClinGen rates the evidence that QRICH1 causes each of these diseases.
syndromic complex neurodevelopmental disorder (autosomal dominant): Definitive. A disorder that involves more than one phenotype associated with the central nervous system, including but not limited to intellectual disability, autism, and seizures (epilepsy), and also a distinctive pattern of other features including dysmorphisms and/or congenital malformations.
Homologues: Orthologues: chimpanzee QRICH1 (100% identical), macaque QRICH1 (100% identical), dog QRICH1 (99% identical), rabbit QRICH1 (99% identical), mouse Qrich1 (99% identical), guinea pig Qrich1 (99% identical), rat Qrich1 (99% identical), tropical clawed frog qrich1 (83% identical), zebrafish qrich1 (63% identical). Paralogues in human: ZMYM4 (28% identical), ZMYM3 (27% identical), ZMYM2 (24% identical), ZMYM6 (13% identical), ZMYM1 (13% identical), GTF2IRD1 (9% identical), KIAA1958 (7% identical), THAP12 (7% identical), GTF2IRD2 (6% identical), GTF2IRD2B (6% identical), ZBED11 (6% identical), ZMYM5 (6% identical), and 6 more.